IL10 (interleukin 10)
Diseases named in the same sentence as IL10 in open-access papers (continued):
Sharing a sentence is not in itself a finding about the gene and the disease.
tumor (continued). "In both the ABX-treated DSS/Apcmin/+ mice and GF Apcmin/+; Il10−/− mice colonized with NC101, TNF blockade with a TNF monoclonal antibody significantly inhibited tumor development." (PMID 33578830, 2021). "This phenotype is characterized by tissue remodeling and angiogenesis properties and the secretion of anti-inflammatory cytokines such as IL-10 and TGF-β9 which support tumor development." (PMID 33771989, 2021). "A recent study on murine as well as patients with non-small cell lung cancer reveals that Tregs secret IL-10 and IL-35 to promote exhaustion of CD8+ TILs to limit effective anti-tumor immunity, resulting in poor prognosis." (PMID 34625124, 2021). "On the contrary, M2 cells are activated by type II cytokines such as IL-4, IL-10, IL-13, and transforming growth factor (TGF)-β, performing a pro-tumor immune response by producing factors as STAT3, which contribute to tumor proliferation." (PMID 33917013, 2021). "The release of high mobility group protein B1 (HMGB1) was demonstrated to drive IL-10 production in TAMs selectively through the receptor for advanced glycation end products (RAGE), leading to an IL-10-rich milieu within the tumor." (PMID 34603327, 2021). "Bregs increase not only in primary tumor tissues but also in the metastatic bone tissues of patients and produce immunosuppressive molecules, such as TGFβ, IL10, and IL35, which promote tumor progression and metastasis directly and indirectly." (PMID 33535613, 2021). ", IL-6, M-CSF, PGE2, IL-10, and VEGF) on DCs would promote anti-tumor efficiency by recruiting and promoting the maturation of DCs." (PMID 34248142, 2021). "TEMs are also capable of secreting large amounts of IL-10 and VEGF, promoting a pro-angiogenic and immunosuppressive environment that inhibits tumor-specific T cell responses in breast tumors." (PMID 33968034, 2021). "In vitro experiments, the expressions of PD-L1, IL-10 and TGF-β in tumor cells were increased after stimulation of cisplatin." (PMID 33814009, 2021). "These include IL-6, IL-8 and TNF-α as well as the immune suppressive cytokines IL-10 and TGF-β, which increase HLA-G expression on tumor cells resulting in promotion of evasion from immune cells." (PMID 35111159, 2021). "In turn, pro-apoptotic TNF-related apoptosis-inducing ligand (TRAIL) and anti-inflammatory cytokines such as Interleukin 10 (IL-10) and transforming growth factor beta (TGF-β) usually lead to tumor suppression." (PMID 34367064, 2021). "TAM-s, which secrete anti-inflammatory and immune suppressive cytokines (e.g., TGFβ and IL10), enhance the expansion of immune suppressive CD4+ Treg cells, inhibit the functions of CD8+ cytotoxic T and NK cells and similarly to tumor cells also express IDO1." (PMID 35366268, 2021). "There is a significant decrease of CD8+/CD4+T cells ratio, NK cells, IL-2, and IFN-γ and a significant increase of T regs, IL-6, IL-1β, TNF-α, IL-10, and PGE2 in CUMS group, indicating the inhibition of immunity in the tumor microenvironment." (PMID 34422050, 2021). "These tolerogenic immune cells release some immunomodulatory molecules, such as TGFβ, IL-10, and PEG2, which foster a tolerogenic environment and block effector immune responses against the tumor growth." (PMID 34485117, 2021). "M2 macrophages secrete Interleukin 10 (IL-10), transforming growth factor-β(TGF-β), and other mediators that stimulate tumor-related angiogenesis and inhibit antitumor immune response." (PMID 34054849, 2021). "Upregulation of VEGF, IL-10 and PGE2 at the tumour site cooperatively promotes Fas ligand expression on tumour endothelial to elicit apoptosis of CTLs, but not Tregs." (PMID 33401460, 2021). "The experiment determined the secretion levels of tumor TNF-α, IL-6, and IL-10 in RAW264.7 cells after treatment with different MP concentrations." (PMID 34436307, 2021).
tumor (continued). "Overall, combination treatment of IL-10-Fc with ACT led to greater survival rates, and remarkably, sustained anti-tumour immune memory with many IL-10-Fc-treated mice surviving tumour re-challenge." (PMID 34621543, 2021). "In the tumor microenvironment, infiltrated Treg cells secrete several immunosuppressive cytokines such as IL-10, TGF-β, and IL-35, which suppress the induction and activation of tumor-specific effector T cells." (PMID 34885241, 2021). "They promote the expansion of tumor cells, epithelial-mesenchymal transition (EMT), and enhance stemness by secreting numerous soluble factors, such as IL-10 and TGF-β." (PMID 34336860, 2021). "To further investigate the effects of VES on inflammatory factors in tumour-bearing mice, we examined TNF-α, IL-12, IFN-γ, IL-2 and IL-10 in the spleen by use of qRT-PCR assays." (PMID 34093795, 2021). "In TME, TAMs facilitate the immune shift of the tumor cells by releasing anti-inflammatory cytokines such as TGF-β and IL-10, which subscribe to the suppression of effector T cell and natural killer (NK) cell cytotoxicity." (PMID 34207035, 2021). "Blockade of IL-10 signalling resulted in abrogation of TAM-H-mediated LEC activation, and the observed increase in tumour cell chemotaxis to inflamed LECs was completely abolished by depleting IL-10R." (PMID 33484377, 2021). "proved that Jianpi Huayu Decoction (JHD) attenuated the expression of IL-10 and TGF-β in tumor tissues and accelerated the differentiation of MDSCs into macrophages and DCs." (PMID 34722304, 2021). "For example, tumor-associated macrophages (TAMs) secrete immunosuppressive cytokines (e.g., interleukin 10 (IL-10) and transforming growth factor-β (TGF-β)) and inhibit host antitumor activity, thereby promoting tumor progression." (PMID 34457003, 2021). "In the tumor, they differentiate into anti-inflammatory M2-like TAM by tumor and TME-derived factors like M-CSF, IL-4, IL-10, and TGF-β." (PMID 34795675, 2021). "GBM cells produce IL10, TGF-β and glucocorticoids, stimulating the expansion of the M2c population, which in turn promotes the proliferation of tumour cells." (PMID 33804731, 2021). "Tregs at the site of the infection or at the TME secrete negative regulatory cytokines, IL-10 and TGF-β, to promote immune suppression, thereby limiting anti-pathogen or anti-tumor activity of effector T cells." (PMID 33717081, 2021). "We show marked reductions in Pdcd1l1, Arg1, Il10 and Tfgb1 in PMN-MDSCs from bone marrow and spleen of tumor-bearing mice." (PMID 34531850, 2021). "Tregs, MDSCs, and M2 macrophages that expressed TGF-β and/or IL-10 were also present in TIL-PDX-PDAC and TIL-PDX-LUAD’s PB and peripheral tissues 4 to 6 months after tumor implantation." (PMID 34081628, 2021). "Another mechanism is the creation of an immune suppressive tumour micro-environment with the help of suppressive cytokines and chemokines such as TGF-β or IL-10." (PMID 34445385, 2021). "Our results show that pro-inflammatory cytokines (TNF-α, IL-12, IFN-γ and IL-2) increase in the spleen of tumour-bearing mice when treated with VES, whereas the anti-inflammatory cytokine IL-10 decreased transcriptionally." (PMID 34093795, 2021). "Treatment with this resveratrol analogue was also found to decrease the number of Tregs and reduce IL-10 and TGF-β secretion in radiation irradiated tumor-bearing mice." (PMID 33802331, 2021). "MEK inhibition also reduces the frequency of Tregs, possibly through reductions in the expression of IL-10 and TGF-β from tumour cells in addition to TAMS and MDSC, potentially due to these subsets being driven by MAPK signalling." (PMID 34960140, 2021). "In this experiment, lycopene managed to enhance IFNβ, IFNγ, IRF1, IRF7, CXCL9, CXCL10 while suppressing IL-4, IL-10, DMNT3a, methylation of IRF1, IRF7 promoters and most importantly, the tumor volume." (PMID 34202203, 2021).
tumor (continued). "Inflammatory mediators, such as tumor necrosis factor (TNF)-α, IL-6, IL-10, and TGF-β, participate in tumor initiation and progression." (PMID 33917793, 2021). "Blood transfusions are associated with promoting a proangiogenic environment inducing tumor growth by releasing cytokines IL6, IL10, and TNFα, and regulatory T-cell activation suppressing the anti-tumoral Th1 response." (PMID 34202030, 2021). "Several marker genes, FOXP3, STAT3, PDCD1, TGFB1, IL10, HMGB1, which are significantly related to the tumor microenvironment induced by radiation, had significant functional differences in the distribution of CD8+T cells clusters." (PMID 33968889, 2021). "Several reports have described the secretion of various factors by tumor-infiltrating immune cells, including TNF-α, IL-10, and TGF-β, as impacting the NF-κB pathway." (PMID 33854604, 2021). "As a consequence, an inactivation of NF-κB and missing NF-κB-dependent production of tumor-promoting factors such as COX2, IDO, or interleukin 10 induction can provide new therapeutic opportunities and minimize negative side effects." (PMID 33809574, 2021). "Studies with NZB IL10 knockout mice evidence the IL10 role in B-1 cell expansion and development of CLL, whereas Mmp10 works by accelerating the tumor growth." (PMID 33659046, 2021). "We observed that the migration effects of TAM-H-treated HDLECs on tumour cells (SiHa) and M2-polarized THP-1 macrophages were significantly decreased by adding anti-IL-10 neutralization antibody to the CM (P < 0.05)." (PMID 33484377, 2021). "Decreased expression of immunosuppressive cytokines such as IL-10 and TGF-β confirmed that the treatment inhibited tumor-suppressing immune signals induced by the tumor cells." (PMID 33632278, 2021). "Furthermore, the incorporation of IL-10 in CAR cassette indeed induced phenotype changes of T cells but neither inhibited the survival of CAR-T cells nor caused an excessive proliferation of tumor cells." (PMID 34392305, 2021). "By contrast, the M2-like macrophages express CD163, CD204, CD206, and STAT3 and secrete high levels of immunosuppressive cytokines including TGF-β and IL-10, which elicit a suppressive effect on cytotoxic CD8+ T lymphocytes, thereby favoring tumor progression." (PMID 34359588, 2021). "M2 macrophages, through increased production of immunosuppressive cytokines (IL-10 and TGF-β) and pro-angiogenic factors (VEGF, PGE2), enabled enhanced tumor growth and progression." (PMID 34830312, 2021). "The CTLs' killing capacity in the liver with IL-10 blockade was lower than that in the spleen (3.18 ± 0.26 tumor cells/CTL/day), implying that IL-10 is one of the reasons to suppress CTL killing." (PMID 33391470, 2021). "Once MDSCs are recruited to the HGG site their expansion and activation are tightly controlled by cytokines (IL-6, IL-10, TGF-β, M-CSF, GM-CSF, INFγ), chemokines (CCR2, and other factors (VEGF) secreted by tumor cells, T cells, microglia, and macrophages." (PMID 33919732, 2021). "RT-qPCR analysis in the present study revealed that Rh2 regulated the expression levels of IL-1, IL-6, IL-10 and TNF-α, which inhibited tumor invasion and angiogenesis." (PMID 34452568, 2021). "In murine metastatic lung tumor models, MDSCs were found to populate the tissue as early as 2 weeks prior to tumor formation; secrete IL-6, S100A8/A9, VEGF, and IL-10 in order to establish the tumor; and recruit additional MDSCs to the lung." (PMID 34482371, 2021). "In our study we found that both IL-10 and Ad-hTERT showed potential in increasing the amounts of CD8+ T cells in tumors and improving specific anti-tumor CD8+ T cells responses." (PMID 33717103, 2021). "IgA+ PCs within prostate tumors induce CD8+ T cell exhaustion and suppress anti-tumor CTL responses through PD-L1 and IL-10, either of which can induce anergy or exhaustion." (PMID 34868013, 2021).
tumor (continued). "As a matter of fact, the constitutive activation of STAT3 can be propagated through IL10, IL-8, and VEGF, from tumor to immune cells, which in turn leads to immune suppression." (PMID 34072037, 2021). "Combined vaccination inhibited tumor progression compared with chitosan or IL-12 alone.Co-formulation of chitosan and IL-12 resulted in higher IFN-γ and IL-4 and decreased IL-10 generation." (PMID 33816349, 2021). "Human IL-10+ TIM-1+ Bregs can also be found infiltrating tumors and have been described to suppress CD8+ and CD4+ T cell anti-tumor responses." (PMID 33995344, 2021). "In contrast, pro-tumorigenic M2-like macrophages activated by IL-4 and IL-13 promote tumor progression and release anti-inflammatory cytokines (e.g., TGF-β, Arginase-I and IL-10)." (PMID 34576180, 2021). "DHA corrects the immunosuppression state of tumor-bearing mice by reducing the secretion of IL-10 and TGF-β and suppressing the number and function of Treg, and then activate the anti-tumor immune response mediated by T cells with CTL as the main body." (PMID 34692496, 2021). "Tumor-promoting TAMs, similarly to other TME cells, by the production of tumor-promoting factors, including VEGF, various cytokines (IL-10, CCL2, CCL17, CCL22, TGF-β), and matrix-degrading enzymes, facilitate the tumor invasion, angiogenesis, and spread." (PMID 34885122, 2021). "In addition, breast cancer has always considered as a cold tumor, the loss of tumor antigens, expression of Fas ligand (FasL) and programmed cell death 1 ligand, and production of immunosuppressive cytokines such as TGF-beta and IL-10 are some of the mechanisms of immune escape." (PMID 34631507, 2021). "As a result, increased IL-10 in TME directly suppressed the generation of CD4+ T cells, thereby impairing tumor immunity." (PMID 33957948, 2021). "On the one hand, TiBcs have the function of promoting tumors by producing IL-10, TGF-β, and IL-35; by the lymphotoxin/ IKKa-BMI1 signaling pathway; or by directly promoting tumor progression through engaging PD-L1/PD-1 molecules." (PMID 33465122, 2021). "Depending upon their microenvironment, TAMs mainly polarize toward “M1”, which secret TNF‐α, IL‐12, and promote antitumor resistance, or “M2” phenotype that secret IL‐10, TGF‐β, and play vital roles in angiogenesis and tumor progression." (PMID 34423566, 2021). "M2 macrophage-derived cytokines promote an immunosuppressive tumor microenvironment, including CCL22, IL-10, and TGF-β1, that were significantly correlated with LILRB1 expression GC patients." (PMID 34485116, 2021). "TAMs can either release immunosuppressive factors such as interleukin 10 (IL-10) and transforming growth factor beta (TGF-β) or release anti-tumor-promoting factors such as IL-12, TNF-α, depending on the conditions within the TME." (PMID 34571905, 2021). "The anti-inflammatory cytokine, IL-10 can paradoxically induce STAT-3 activation, which also leads to induction of tumor cell proliferation." (PMID 34307156, 2021). "STAT3 phosphorylation (STAT3 activation) and increased expression of interleukin-10 (IL-10) were detected in 53.1% and 78.1% of PCNSL tumor samples, respectively." (PMID 33996566, 2021). "Neutrophils which exist in tumor microenvironment are capable of producing IL10 and CCL3 to promote tumor growth." (PMID 34123808, 2021). "Analysis of specific genes involved in CD4+ differentiation and function revealed differential methylation status of TBX21, GATA3, RORC, FOXP3, IL10 and IFNG in tumor CD4+ T-cells." (PMID 34012510, 2021). "Paclitaxel or carboplatin treatment in mice with MMTV-PyMT tumors was counteracted by increased IL-10 secretion from TAMs, leading to downregulated IL-12 production in dendritic cells and the inhibition of CD8+ T-cell anti-tumor activity." (PMID 34209703, 2021). "Tumour-infiltrating CD73+γδ1 T cells express high levels of IL-4, IL-17A, IL-10, GM-CSF and TGF-β, and exert immunosuppressive functions mainly via the adenosine-mediated pathway." (PMID 32345959, 2020).
tumor (continued). "Blockade of IL-10 in pre-clinical models, either directly or via depletion of macrophages has been shown to improve CD8+ T cell mediated anti-tumor immune responses in both murine and human systems." (PMID 32508825, 2020). "In RS, PD-1 expression is a hallmark of recently described « Regulatory B-cells », which interact with tumor microenvironment by producing inhibiting cytokines such as TGF-β and IL-10, impairing T lymphocytes anti-tumoral function." (PMID 33381116, 2020). "In the context of ovarian cancer, TAMs are one of the most abundant immune populations and produce cytokines such as IL-10 and TGF-β, as well as the chemokine CCL22, which attracts Tregs to the TME, assisting in the pro-tumour microenvironment." (PMID 32183059, 2020). "Th2 cytokines such as IL-4, IL-10, and IL-13 are able to induce M2 macrophages which have reduced cytotoxic activity and dampens CD8 T cell-mediated anti-tumor activity." (PMID 33117354, 2020). "Resveratrol, Lipoxin, Glucosides of Paeony have also inhibited Bregs through STAT3 and/or ERK inactivation leading to a reduction in IL-10 and TGF-β levels thus exerting an anti-tumour effect." (PMID 31901949, 2020). "In brain tumors, GAMs are activated by tumor secretion of IL-10 and TGF-B to become an anti-inflammatory and tumor-promoting M2 phenotype." (PMID 33511267, 2020). "In vivo studies on mice models have shown that IL-10 seems to be one of the pillars of EMT and of obtaining the stemness of tumor cells." (PMID 33228048, 2020). "Tumor cells consistently release many immuno-suppressive and pro-inflammatory factors such as vascular endothelial growth factor (VEGF), TGF-β, IL-10, PGE2, eNOS, which induce tumor-infiltrating immune cells to be tolerance." (PMID 32754587, 2020). "cGAS/STING pathway is also related to tumor microenvironment remodeling and the production of anti-tumor cytokines such as indoleamine 2,3-dioxygenase (IDO), IL-10 and ISGs, together inhibiting tumor growth and improving the survival." (PMID 35006429, 2020). "Tumor-infiltrating T, B, and NK cell levels and plasma concentrations of Th1 (IL-2, IFN-γ, and TNF-α), Th2 (IL-4, IL-5, IL-6, and IL-10), Th9 (IL-9), and Th17 (IL-17A, IL-17F, IL-21, and IL-22) cytokines were evaluated." (PMID 32802733, 2020). "The pDC dysfunction can be induced by soluble factors derived from tumor cells, necrotic cells or other immune cells, such as PGE2, TGF-β, IL-10, IL-3, Vasoactive Intestinal Peptide, Wnt5a and HMGB1." (PMID 32054102, 2020). "IL-10 inhibits CD4+ T-cell response induced by mesothelin, an immunogen involved in promoting metastasis and tumor proliferation and a potential therapeutic target in PC." (PMID 32012917, 2020). "Our data suggest that higher expressed ICOSL tumor tissues express higher levels of IFN-γ and IL-17, and less IL-10 and IL-4, compared with ICOSL low expressed tumor tissue, indicating that ICOSL promotes Th1 and Th17 response in NPC patients." (PMID 31998801, 2020). "In tumors, IL-4, IL-13, IL-10, TGF-β, and CXCL5 increase tumor cell growth and metastasis through efferocytosis-induced cell clearance and macrophage polarization in the TME." (PMID 32346605, 2020). "CM from both tumor cell lines induced M2 polarization as shown by the increased expression of CD163, FN1, and IL10 mRNAs, and a dramatically reduced expression of these M2 markers was observed in the ezrin-depleted cells." (PMID 33086476, 2020). "Macrophages in the tumor microenvironment are mainly M2-polarized TAMs and release anti-inflammatory cytokines (e.g., IL-1, TNF-a, IL-10)." (PMID 32222879, 2020). "The continuous activation of STAT3 in tumor cells increases the expression of cytokines (transforming growth factor β [TGF-β] and IL-10) and then promotes tumor development and metastasis in a positive-feedback manner." (PMID 32487755, 2020). "Under SPF conditions total tumor incidence in DKO and MSH2loxP/loxP Vil‐cre was again similar, but greatly reduced in IL‐10−/− mice." (PMID 32350866, 2020).